AKR1B10 (aldo-keto reductase family 1 member B10)
Diseases named in the same sentence as AKR1B10 in open-access papers (continued):
Sharing a sentence is not in itself a finding about the gene and the disease.
colon carcinoma (16 papers, 2012 to 2025). "Liu et al28 demonstrated that AKR1B10 expression was substantially associated with T-stage and clinical stage of colon cancer, and knockdown of AKR1B10 substantially attenuated tumor cell proliferation and clonogenic capacity." (PMID 37823316, 2023). "With the help of these powerful aldo-keto reductase inhibitors, it may be possible to synthesize potential new pharmaceuticals that cure colon cancers associated with aberrant expression of the AKR1B1 or AKR1B10 protein." (PMID 36301939, 2022). "Upregulation of AKR1B10 in chemotherapy-resistant medulloblastoma D341 and colon cancer HT29 cancer cell lines underscore the utility of this enzyme as a biomarker of drug resistance." (PMID 39055885, 2024). "Our result also showed that colon tumor has a low expression of AKR1B10 and patients with higher expression of AKR1B10 have better overall survival." (PMID 35178443, 2022). "In medullablastoma and colon cancers, AKR1B10 has been shown to be involved with the metabolic deactivation of the chemotherapeutic agents cyclophosphamide and mitomycin-c." (PMID 30941001, 2019). "In colon cancers, studies reported that the up-regulated expression of AKR1B10, AKR1C1, AKR1C2 and AKR1C3 contributed to chemotherapeutic drug resistance indirectly, by reducing oxidative stress generated by these chemotherapeutic agents." (PMID 27635343, 2016). "AKR1B10 has been shown to accelerate the production of proinflammatory cytokines in colon cancer." (PMID 40455785, 2025). "Moreover, they found that AKR1B10 promoted the production of IL-1α and IL-6 in colon cancer cells through the activation of NF-κB, and the proliferation of cancer cells was inhibited by knocking down AKR1B10, which contrasts some previous findings." (PMID 39737179, 2024). "Our study purposes to discover the potent aldo-keto reductase inhibitors that may help to synthesize effective molecule with drug-likeness for the treatment of colon cancer specifically occur from the abnormal expression of either protein AKR1B1 or AKR1B10." (PMID 35807227, 2022). "The aberrant expression of aldo keto reductases (AKR1B1 & AKR1B10) has been extensively studied in different types of cancer especially the colon cancer but a very few studies have yet been reported regarding the discovery of inhibitors for the treatment of colon cancer by targeting these isozymes." (PMID 36301939, 2022). "The treatment of human colon cancer SW-480 and HT-29 cell lines with proteasome inhibitors known to increase the expression of Nrf2-regulated genes induced AKR1B10 expression suggesting that AKR1B10 could be a target of the Nrf2 transcription factor." (PMID 22876234, 2012).
lymph node metastasis (13 papers, 2016 to 2024). "By contrast, patients who underwent neoadjuvant chemotherapy showed that high AKR1B10 expression was associated with lymph node metastasis and a poorer prognosis, along with a weak response to neoadjuvant chemotherapy." (PMID 34063865, 2021). "In contrast, GC patients with AKR1B10 overexpression had advanced lymph node metastasis, fewer tumor regression, and worse overall survival (OS) compared to those with negative expression of AKR1B10." (PMID 36661656, 2022). "On the other hand, the expression of AKR1B10 increased with a trend from early stage to advanced stage, and a similar finding was also mentioned in the status of lymph node metastasis." (PMID 36661656, 2022). "At the same time, we demonstrated that the expression of AKR1B10 in TNM stage III–IV patients or patients with lymph node metastasis was lower than that in control group in a significant way." (PMID 34552036, 2021). "It is possible that this result was confounded by the fact that their patients with high AKR1B10 expression also had higher tumor stage and higher rate of lymph node metastasis than patients with low AKR1B10 expression." (PMID 28181486, 2017). "We further confirmed that the mRNA expression level of AKR1B10 correlated with TNM stage and lymph node metastasis, and that a high AKR1B10 mRNA expression level was related to a shorter DFS and OS." (PMID 26948042, 2016). "These are in consistence with the clinical settings where AKR1B10 expression correlates with lymph node metastasis and worse disease-free survival." (PMID 27248472, 2016). "In contrast, GC patients with overexpression of AKR1B10 were found to have advanced lymph node metastasis, fewer tumor regression, and worse overall survival (OS) than those without AKR1B10 expression." (PMID 36661656, 2022). "Furthermore, AKR1B10 expression levels in NPC were negatively correlated with tumor size (r = −0.399, p < 0.001) and lymph node metastasis (r = −0.326, p < 0.001)." (PMID 26949513, 2016). "AKR1B10 mRNA level correlated with serum AFP level, TNM stage, and lymph node metastasis." (PMID 26948042, 2016). "In addition, AKR1B10 decreased in patients with lymph node metastasis in a significant way compared with patients without." (PMID 34552036, 2021).
non-small cell lung carcinoma (13 papers, 2013 to 2025). A group of at least three distinct histological types of lung cancer, including non-small cell squamous cell carcinoma, adenocarcinoma, and large cell carcinoma. "AKR1B10 is primarily expressed in the colon and small intestine but over-expressed in several types of cancer, such as non-small cell lung carcinoma and breast cancer." (PMID 32968147, 2020). "It is possible that it may regulate cell proliferation in non-small cell lung cancer as increased AKR1B10 expression is correlated with changes in genes involved in the cell cycles such Ki-67, cyclin E, GalNAcT3, and GnT-V." (PMID 24391771, 2013). "The present research investigates the counterintuitive effects of sublethal chemotherapy doses in non-small-cell lung cancer (NSCLC), focusing on their role in enhancing cancer cell malignancy and the role of Aldo-keto reductase family 1 member B10 (AKR1B10) in this process." (PMID 39001490, 2024). "Moreover, AKR1B10 and AKR1C1 are overexpressed in non-small cell lung cancer and strongly correlate with Nrf2 activation." (PMID 35204145, 2022).
lung adenocarcinoma (11 papers, 2019 to 2024). A carcinoma that arises from the lung and is characterized by the presence of malignant glandular epithelial cells. "In hepatocellular carcinoma, LINC00665 regulates cell cycle pathways, whereas in lung adenocarcinoma, it acts as a ceRNA and binds miR-98, subsequently activating the aldo–keto reductase family 1 member B10 (AKR1B10)–extracellular-signal-regulated kinase (ERK)-signaling pathway." (PMID 32983239, 2020). "In addition, the AKR1B10-ERK signaling pathway was abnormally expressed in lung adenocarcinoma." (PMID 36028503, 2022). "When AKR1B10 is silenced in lung adenocarcinoma cells, it suppresses their extravasation through the BBB in vitro, ex vivo microfluidic chip, and in vivo models; moreover, AKR1B10 silencing induced the downregulation of metastatic cells’ expression of matrix metalloproteinase MMP-2 and MMP-9." (PMID 39408656, 2024). "PEM drug-sensitivity was assessed in the preclinical BM model of PC9 lung adenocarcinoma cells and the BM cells with or without AKR1B10 interference in vitro and in vivo." (PMID 37587486, 2023). "Data from an earlier study on lung adenocarcinoma showed that miR-98 expression negatively correlated with LINC00665 expression and that the latter acted as a ceRNA to competitively bind miR-98, thereby activating the AKR1B10–ERK-signaling pathway to facilitate cell proliferation and metastasis." (PMID 32983239, 2020).
cholangiocarcinoma (9 papers, 2022 to 2026). A carcinoma that arises from the intrahepatic biliary tree (intrahepatic cholangiocarcinoma) or from the junction, or adjacent to the junction, of the right and left hepatic ducts (hilar cholangiocarcinoma). "In cholangiocarcinoma, AKR1B10 in aldosterone reductase family is associated with glycolysis and malignant phenotype of cancer cells." (PMID 37582735, 2023). "CGA potently inhibits cholangiocarcinoma cell proliferation, migration, and invasion by targeting AKR1B10, while inducing apoptosis to combat the disease." (PMID 40509442, 2025). "An analysis of the TCGA database indicated an overexpression of AKR1B10 in various tumor cells, with a notably high expression in cholangiocarcinoma." (PMID 38931461, 2024). "Under the action of METTL3, the stability and expression of AKR1B10 mRNA were improved, which promoted the growth and glycolysis of cholangiocarcinoma." (PMID 37582735, 2023). "Consequently, the elevated AKR1B10 promotes a glycolytic phenotype in cholangiocarcinoma (CCA) cells, characterized by increased glucose uptake and lactate production, which ultimately drives malignant progression." (PMID 41522342, 2026). "CGA may exert its anti-cholangiocarcinoma effects by targeting AKR1B10 and subsequently influencing AKT." (PMID 38931461, 2024). "However, there is limited research on AKR1B10 in cholangiocarcinoma, and currently, there are no reported studies on its role as a therapeutic target." (PMID 38931461, 2024).
steatosis (9 papers, 2012 to 2025). Increased lipid within the cytoplasm of cells. "Six progress-related genes (AKR1B10/SPP1/CD24/UBD/FABP4/STMN2) were found remarkably correlated with steatosis, ballooning, inflammation, fibrosis, and NAS in the progress of Normal/NAFL/NASH." (PMID 33574818, 2020). "The most striking examples in this respect were KRT23 and AKR1B10, which we found to be highly differentially expressed in steatohepatitis compared to steatosis and normal liver." (PMID 23071592, 2012). "Immunohistochemical expression of AKR1B10 in liver parenchyma of patients with steatohepatitis, steatosis and chronic hepatitis C." (PMID 23071592, 2012). "Similarly, pharmacological inhibitors of AKR1B10 were capable of reducing steatosis, fibrosis, and inflammation in mouse with non-alcoholic steatohepatitis." (PMID 36028503, 2022). "Of the three protein expressed in well-differentiated HCCs, only AKR1B10 was upregulated in preneoplastic conditions, and a steatosis-related factor might influence its expression." (PMID 24747592, 2014). "Taken together, all of these findings suggest that AKR1B10 might play a role in the molecular basis of steatosis-related hepatocarcinogenesis." (PMID 24747592, 2014). "AKR1B10 expression in cases with steatohepatitis as assessed by the immunohistochemical AKR1B10 score was significantly higher as compared to the AKR1B10 expression in the steatosis and chronic hepatitis C cases (p = 0.003 and 0.006, respectively)." (PMID 23071592, 2012). "The heatmap shows the relative expression levels of the four genes (AKR1B10, FABP4, GNMT, and THBS1) in normal, steatosis, and steatohepatitis tissues across the three training datasets." (PMID 39781352, 2025). "Importantly, we found that lysosomal DEPs, including CTSB/D/Z, LIPA, DPP7 and GLMP, and mitocondrial DEPs, AKR1B10, and VAT1 had been connected with liver fibrosis, damage, and steatosis in previous studies, validiting our dataset." (PMID 34440927, 2021). "In human HepG2 cells, PXR activation by rifampicin promoted steatosis via induction of SREBP-1 pathway (mainly SREBP-1a), whereas PXR silencing enhanced AKR1B10 expression, which subsequently stabilized the acetyl-CoA carboxylase, thereby promoting de novo lipogenesis." (PMID 31374856, 2019). "It is the murine ortholog of AKR1B10 that is a significantly upregulated gene in the livers of human MASH patients, and its pharmacological inhibitors of AKR1B8 significantly reduced the pathological features of MASH, such as steatosis, inflammation, and fibrosis in mouse." (PMID 39595946, 2024). "Furthermore, AKR1B10 did not correlate with steatosis grade, but did significantly with fibrosis score, indicating that AKR1B10 is a marker of MASH progression." (PMID 37686029, 2023). "However, AKR1B10 expression in liver tissues with steatosis or chronic hepatitis C was not different (p = 0.351)." (PMID 23071592, 2012).
Cirrhosis (8 papers, 2014 to 2023). A chronic disorder of the liver in which liver tissue becomes scarred and is partially replaced by regenerative nodules and fibrotic tissue resulting in loss of liver function. "In HCC patients treated with surgical resection (n = 92) or liver transplantation (n = 76), AKR1B10 overexpression was significantly associated with lower tumor classification, underlying viral hepatitis, or cirrhosis." (PMID 30959792, 2019). "AKR1B10 is significantly overexpressed in lower tumor stages with underlying cirrhosis or viral hepatitis, whereas it is down-regulated in advanced tumor stages." (PMID 26949513, 2016). "We found that AKR1B10 expression is upregulated in chronic hepatitis or cirrhosis, preneoplastic conditions that predispose to HCC, in association with hepatic steatosis." (PMID 24747592, 2014). "In the present study, we demonstrated that AKR1B10 expression levels were significantly higher in livers with chronic hepatitis or cirrhosis, which are preneoplastic conditions underlying HCC, than in normal livers, and that AKR1B10 expression was still higher in HCCs." (PMID 24747592, 2014). "AKR1B10 was significantly overexpressed in the early stage of diseases such as cirrhosis or viral hepatitis and down-regulated in the advanced stage of poorly differentiated tumors." (PMID 37039038, 2023). "AKR1B10 was upregulated in hepatocytes from patients with NASH (GSE129933) or cirrhosis (GSE136103) compared with hepatocytes from their respective control subjects." (PMID 35563425, 2022). "Compared with that in normal liver tissues, AKR1B10 was significantly upregulated in cirrhosis (P < 0.0001), liver cell dysplasia (P < 0.0001) and HCC tumors (P < 0.0001)." (PMID 31598161, 2019). "Meta-analysis in Oncomine database revealed that AKR1B10 was significantly upregulated in cirrhosis, liver cell dysplasia and HCC compared with normal tissues (all P < 0.05)." (PMID 31598161, 2019). "Consistent with previous reports, we found that AKR1B10 was significantly upregulated in cirrhosis, liver cell dysplasia and HCC tumors compared with normal livers." (PMID 31598161, 2019). "Additionally, AKR1B10 was significantly higher in HCC tumor tissues than that in cirrhosis and in liver cell dysplasia." (PMID 31598161, 2019). "Additionally, AKR1B10 was significantly higher in HCC tumor tissues than that in cirrhosis (P < 0.01) and in liver cell dysplasia (P < 0.05)." (PMID 31598161, 2019). "Moreover, the role of AKR1B10 in chronic hepatitis or cirrhosis, which are considered preneoplastic conditions for HCC, has not been fully elucidated." (PMID 24747592, 2014). "However, the stepwise upregulation of AKR1B10 from chronic hepatitis or cirrhosis to HCC might indicate its potential role in the early stage of hepatocarcinogenesis." (PMID 24747592, 2014). "Meanwhile, AKR1B10 mRNA ranked at the top 2% and 9% of the significantly altered genes in HCC and cirrhosis respectively (p < 0.001)." (PMID 28978011, 2017). "Considering the secretory characteristics of AKR1B10 and the spectrum of NAFLD ranging from NAFL to NASH to cirrhosis and HCC, we aimed to evaluate the feasibility of AKR1B10 as a blood biomarker of NASH and fibrosis with parallel analyses of other blood and imaging biomarkers." (PMID 35563425, 2022). "AKR1B10 has been reported to be increased in some cancers, including HCC as well as chronic liver diseases including NASH and fibrosis/cirrhosis." (PMID 35563425, 2022). "No obvious correlation was observed between AKR1B10 mRNA expression and gender, age, cirrhosis, tumor size or number, presence of macrovascular invasion, tumor stage, or degree of tumor cell differentiation." (PMID 28181486, 2017). "Based on the findings reported to date, we speculate that AKR1B10-positive cells may interact with other factors, such as HCV/HBV viral load or presence of cirrhosis to activate or repress additional pathways, thereby contributing to a number of specific HCC subtypes with variable prognoses." (PMID 30959792, 2019).
chronic hepatitis C (7 papers, 2012 to 2023). "Two similar studies have demonstrated that patients with chronic hepatitis B and chronic hepatitis C expressed high levels of AKR1B10 and its expression acted as an independent risk factor for HCC development." (PMID 36845547, 2023). "Recently, we conducted a study demonstrating that AKR1B10 upregulation was a risk factor for HCC development in chronic hepatitis C patients." (PMID 24747592, 2014). "Recently, we analyzed the expression profiles of approximately 41,000 genes in patients with chronic hepatitis C and found that AKR1B10 was upregulated in the livers of chronic hepatitis C patients at high risk of HCC." (PMID 24747592, 2014). "AKR1B10 was up-regulated in association with serum AFP, and was an independent risk factor for HCC in chronic hepatitis C patients, suggesting its possible involvement at a very early stage of hepatocarcinogenesis." (PMID 22681639, 2012). "In contrast, hepatocytes in livers with chronic hepatitis C showed prominent AKR1B10 immunoreactivity in the cytoplasm, or in the cytoplasm and nucleus." (PMID 22681639, 2012). "Further studies are warranted to better understand the mechanism of AKR1B10 regulation in chronic hepatitis C." (PMID 22681639, 2012). "Interestingly, our earlier metabolomic investigation of patients with chronic hepatitis C revealed a clear induction of the aldose reductase AKR1B10 with enhanced catabolism of both glucose and galactose, although the stage of hepatic fibrosis in these patients was not reported." (PMID 36766828, 2023).